IL6 (interleukin 6)
Diseases named in the same sentence as IL6 in open-access papers (continued):
Sharing a sentence is not in itself a finding about the gene and the disease.
tumor (continued). "As with IL-6, IL-1ß also interacts with other cell types and triggers other pathways in the TME directly affecting tumor growth, invasion and angiogenesis, by inducing the secretion of angiogenic factors by tumor and stromal cells." (PMID 33059744, 2020). "We observed a non-significant difference in IL6 gene expression between tumor and non-tumor in AA and a 5.2-fold increase of the cytokine in tumors from CA as well as a non-significant reduction (−3.18 fold) of the IL6R gene only in CA." (PMID 32983990, 2020). "It is known that tumor cells release paracrine factors able to attract and/or activate CAFs; for instance, transforming growth factor (TGF)-β1, interleukin (IL)-1, and IL-6 have been reported in the activation of fibroblasts." (PMID 31906302, 2020). "However, our data also show that the levels of CXCL1, IL6, IL8, and VEGF for myeloid cells were similar to that of the tumor cells alone." (PMID 32316245, 2020). "In the tumor tissues, M5D1 significantly decreased IL-6 and increasd IFN-γ." (PMID 32514619, 2020). "In line with the key roles of IL-6 in enhancing tumor cell stemness, the JAK-STAT3 pathway was connected to or proven to take part in these events; also, the Notch pathway was suggested to mediate IL-6-induced stemness in BC." (PMID 33585241, 2020). "MSCs, especially MSCs isolated from the tumor stroma, secrete higher levels of IL‐6 70, 103 than other non‐tumor cells, which together with PGE2 can participate in suppression of NK cell activity and facilitate tumor cell dissemination and metastasis." (PMID 31608444, 2020). "The stromal cells, in turn, secrete paracrine growth factors such as vascular endothelial growth factor (VEGF), insulin-like growth factor (IGF), interleukin-6 (IL-6), Wnt, platelet-derived growth factor (PDGF), and bone morphogenetic proteins (BMP) to promote tumor growth." (PMID 32957513, 2020). "They indicated that the cytokines secreted by these cells (IL-1β, Il-6, IL-8, IL-23 and TGF-β) could explain the high infiltration of Th17 cells at tumor site." (PMID 32121394, 2020). "Here, IOP can inhibit the production of IL-6, TNF-α and COX-2 in colon tissue, suggesting that this may be one of the potential mechanisms by which IOP exerts its anti-tumor effect." (PMID 33603669, 2020). "IL-6 also represents one of the main signals in communication between cancer cells and their non-malignant neighbours within the tumour niche." (PMID 33114676, 2020). "CAFs also secrete high levels of Interleukin 6 (IL‐6) and cyclooxygenase 2 (COX‐2), factors correlated with inflammation, angiogenesis and proliferation support, this way circumventing apoptosis and promoting tumour progression." (PMID 33173111, 2020). "In turn, IL-6 induces the production of CXCL7 by MSCs, which has been shown to promote tumor invasiveness and metastasis in murine models, as well as tumor growth through interaction with the tumor receptor CXCR2 that, in turn, induces the synthesis of other cytokines including IL-6 and IL-8." (PMID 33059744, 2020). "In TAMs-tumor cells in vitro co-culture model, tumor necrosis factor-related apoptosis-inducing ligand (TRAIL) reprograms TAMs to M1-like phenotype by inducing expression of proinflammatory cytokines like IL1B, IL6, TNFα." (PMID 32219066, 2020). "In a spontaneous model of breast cancer, a vigorous exercise training protocol of 20 weeks (60 min/d, 20 m/min, 5% inclination and 6d/wk) was able to reduce the volume and number of tumours (metastasis) accompanied by decreased plasma concentration of MCP-1 and IL-6." (PMID 33371214, 2020). "IFN-α/β and IFN-γ favor tumor control, whereas TGF-β, IL-6, and CSF-1 favor tumor growth." (PMID 33297519, 2020). "This reduction in IL6 secretion, may allow hADSCs-IL2 to have an inhibitory effect on tumor growth and proliferation compared to native hADSCs." (PMID 32560387, 2020).
tumor (continued). "Correlation between chromogranins and inflammatory parameters (high sensitivity C reactive protein, interleukin-6, and white blood cell count) showed that CgA was not correlated with these parameters in any of the tumor groups (p ≥ 0.0824)." (PMID 33383764, 2020). "MSCs have been also shown to improve tumor progression, after injection to the tumor site, through secretion of several growth factors such as TGF-β, epidermal growth factor receptor, periostin, ANG1, PDGF, insulinlike growth factor, and IL-6." (PMID 32793565, 2020). "Finally, IHC found that preoperative FOBT-positivity in patients was significantly associated with higher TAMs infiltration and higher expression of IL-6 and TNF-α in tumor tissues than in the preoperative FOBT-negative group." (PMID 33643891, 2020). "An interesting point is that even if tumor cells do not express IL-6 receptor (IL-6R), the soluble form of IL-6R can activate IL-6." (PMID 32674405, 2020). "Interleukin-6 (IL-6), IL-10, and TNF are important triggers of myeloid origin inhibiting the proliferation and recruitment of MDSCs and are considered to be the main coordinator of immunosuppressive tumor microenvironment." (PMID 32547401, 2020). "In this study, inflammatory cytokines that could enhance the tumourigenic process such as IL-6, IL-1β, and TNF-α were decreased in FLP-treated MO mice in the tumour tissues and serum compared to those of MO mice, which is in accordance with previous studies." (PMID 32308722, 2020). "It was reported that cytokines and chemokines, such as IL-6 and RANTES, produced by the tumor cells could promote the generation of MDSCs, which might explain that CM from high single-dose IR cells lead to less differentiation or proliferation of MDSCs." (PMID 32117702, 2020). "Interestingly, most deregulated genes, such as IL6, RelB, RelA, Plac8, ITGA5, CXCL12 and FN1, among other cytokines and growth factors, have been involved in tumor growth and progression." (PMID 32848147, 2020). "In addition, both MMP2 and TGF-β1 proteins as well as IL6 and IL8, whose secretion levels were high in hADSCs-IL2, are important participants in EMT of tumor cells." (PMID 32560387, 2020). "Mechanistically, tumor lysates stimulated SOCS3 knockout macrophages in vitro, their STAT3 phosphorylation is enhanced and TNF-α and IL-6 are reduced, and higher levels of MCP2/CCL8 via STAT3 are produced to combat tumor metastasis in contrast to normal macrophages." (PMID 33224886, 2020). "Neither secretion of adipocyte specific cytokines (leptin and adiponectin) nor angiogenesis factors (VEGF, HGF) or MCP1 and IL6 discriminate fat tissues from tumor-bearing (AdipTa or AdipTd) and tumor-free breasts (AdipN)." (PMID 32974182, 2020). "Several products (such as IL-6, PGE2, ROS) from tumor cells and other immune cells can impair moDC differentiation and survival and block their antigen presenting functions, leading to a tumor-promoting phenotype." (PMID 32486257, 2020). "Tumor supporting cytokines are released from tumor and stromal cells upon AT1 receptor activation via Ang II including, TGF-β and Interleukins (IL-1α, IL-1β, IL-6, IL-8)." (PMID 32503281, 2020). "Future studies may explore whether IL-6 plays a role in resistance to cetuximab-induced ADCC, perhaps in a tumor/immune cell co-culture model." (PMID 31914141, 2020). "In contrast, in the absence of stemness gene amplifications, the proliferation of EpCam+ tumor cells from patient Ti41749/17 was reduced, and EpCam+ tumor cells from patient Ti41749/17 did not form mammospheres, even under the influence of IL-6." (PMID 32523653, 2020).
tumor (continued). "In tests on mice, berberine reduced tumor vasculature by inhibiting the activity of factors responsible for angiogenesis, e.g., VEGF, inflammatory mediators: IL-6, IL-1β, TNF-α and a factor stimulating the formation of macrophage colonies—GM-CSF (granulocyte macrophage colony-stimulating factor)." (PMID 33198257, 2020). "Many studies have reported that a series of proangiogenic cytokines are enriched in tumor-derived EVs, such as VEGF, fibroblast growth factor (FGF), interleukin (IL)-6, IL-1α, and tumor necrosis factor alpha (TNF-α), which directly contribute to tumor angiogenesis." (PMID 33628730, 2020). "The blockade of IL‐6 could not only inhibit tumour growth, but also promote the accumulation of CD8+ TILs in tumour." (PMID 31642585, 2020). "CAFs can induce hepcidin in tumor cells through interleukin 6 (IL-6) secretion and stimulation of signal transducer and activator of transcription 3 (STAT3) signaling, illustrating one of the mechanisms where iron metabolism underpins tumor-stroma crosstalk." (PMID 32328462, 2020). "While there are a few reports indicating that IL-6 cytokines do not affect MCF7 tumor cell proliferation in vitro, these studies typically looked at early time points (e.g., 48–72 h of treatment)." (PMID 32023849, 2020). "IL-6/STAT3-dependent Oct4 expression has also been observed in HCC cell lines and tumor homografts." (PMID 33343368, 2020). "IL-6 has been reported to promote cell proliferation, affect insulin growth factor (IGF), and result in insulin growth factor binding protein (IGFBP) 3 inhibition, thereby contributing to an environment favoring tumor proliferation in patients with NSCLC." (PMID 33059654, 2020). "Taking into consideration that M2 macrophage polarization and some macrophage-derived cytokines (e.g., IL6, IL8, TNFα) stimulate EMT in tumors and CSC niche formation, one can suggest that tumor cell-secreted GRP78 promotes cancer stemness via macrophage-involving mechanisms." (PMID 32268506, 2020). "Here, Notch family members could lead to IL-6/STAT3 activation, and in other cases the IL-6/STAT3 pathway has given rise to Notch activation, eventually promoting a diversity of tumor-promoting processes in BC cells." (PMID 32605277, 2020). "IL-6 activation induces JAK/STAT3 pathway in both tumor cells and tumor-infiltrating immune cells." (PMID 33080912, 2020). "As for humoral factors, VEGF, macrophage migration inhibitory factor (MIF), IL-6, IL-4/13, IL-10, TGFβ, POSTN, colony-stimulating factor-1 (CSF-1), CCL2, CXCL12, and COX-2/PGE2 directly or indirectly regulate the immunosuppressive tumor microenvironment." (PMID 32707672, 2020). "Simulations delineated mechanisms contributing to observed cell and cytokine (IL6) dynamics and predicted that initial step-fractionated dosing limits systemic T-cell activation and cytokine release without compromising tumor response." (PMID 32859946, 2020). "However, cytokines such as IL6, IL8, CXCL1, and VEGF can accelerate tumor progression by promoting tumor cell proliferation, migration, invasion, angiogenesis, and stemness-related factor upregulation." (PMID 33116117, 2020). "Mouse IL-6 or IL-8 was undetectable (data not shown), indicating that the source of the cytokines was tumour derived rather than being from stromal tissue." (PMID 31772325, 2020). "Thus, TF expression is induced both in normal cells (mostly vascular or fibroblastic-type cells and monocytes after injury or infection) and in tumor cells by a variety of inflammatory and growth factors including VEGF, TNFα, IL-1β, IL-6, or IL-8." (PMID 32152404, 2020). "Present in the ECM, it promotes tumor cell adhesion, proliferation and migration through integrin binding and activation of the YAP signaling pathway, and through the secretion of cytokines such as IL-6 and TGF-β that promote immune escape and EMT." (PMID 33114328, 2020).
tumor (continued). "Others have described modulation of cytokine production of IL-1α, IL-1β, IL-2, IL-4, IL-6, IL-8, IL-10, IL-17A, TNF-α, and IFN-γ on tumor cells treated with conventional PDT, but their increase or decrease seems to highly depend on the cell line and PDT protocol used." (PMID 32326519, 2020). "In addition, the use of NF-κB or STAT3 inhibitor decreased PD-L1 expression in adi-CM-treated tumor cells, which provided more evidence that TNF-α and/or IL-6 signaling mediated the regulation of PD-L1 in adi-CM-treated tumor cells." (PMID 32477009, 2020). "We also tried to quantify the IL-6 and IL-6R levels using real- time PCR, but the tumor sample was not large enough to evaluate them." (PMID 32138303, 2020). "In addition, α-MGT also suppressed the activation of STAT3 induced by IL-6 or EGF, two major growth factors of tumour cells that activate STAT327." (PMID 31980595, 2020). "Regardless of the tumor type or tumor site, Ly6c1high CAFs (iCAFs) showed enrichment for Il33, Il6, Ccl7, Cxcl1 and Cxcl12 whereas α-SMAhigh CAFs (myCAFs) expressed high levels of Tgfb1, Tgfb2 and Ctgf." (PMID 32455670, 2020). "Whether MAGI1 is part of this mechanism, and whether this protein is possibly regulated by other tumor-promoting mediators of inflammation (e.g., TNF, IL6) is an attractive hypothesis that deserves further investigations." (PMID 31963297, 2020). "The expression of ACTA2 may stimulate the release of IL‐6 by CAFs to induce EMT and promote the progression of tumor phenotype from noninvasive to invasive phenotype." (PMID 32786144, 2020). "Specifically, we again observed CXCL10 and IL-6 production that was significantly higher in co-culture compared to the vasculature alone, regardless of tumor cell STING." (PMID 33013881, 2020). "Besides, cytokines such as TNF-α, IL-1α/β, or IL-6 can trigger STAT3 signaling transduction and NF-κ B transcription, promoting tumor cell proliferation and survival as well as immune response." (PMID 32410986, 2020). "In addition, we recently observed that caspase-8 expression in GBM played a non-canonical function sustaining NF-κB activation, cytokine production (i.e., IL-6, IL-8, IL-1β, MCP-1, and VEGF-α), and tumor growth in vivo." (PMID 32545574, 2020). "Interestingly, however, chronic circulating markers of inflammation (i.e., IL-6, CXCL1) were observed in mouse models even after tumor resection, suggesting long-term changes due to the cancer or surgery even when the tumor is no longer present." (PMID 33302472, 2020). "In addition, IL-6 is a useful salivary biomarker in OSCC and its expression in cancer tissues has also been shown to be involved in tumor progression." (PMID 32455867, 2020). "Tumor-associated macrophages (TAMs) acquired M2 phenotype could produce cytokines, including IL-6, IL-10, and C-C motif chemokine ligand 20 (CCL20), to reduce anti-tumor immune response and support tumor growth." (PMID 32723346, 2020). "Interestingly, our qPCR data with validated species-specific primers shows that most of the IL6 was of host origin, while IL13 was expressed by tumor cells." (PMID 33414685, 2020). "A negative correlation was noted between MCF-7 cell viabilities and M1/M2 cytokine secretion ratios ((IL-6 + TNF-α)/IL-10) in the corresponding MCM, suggesting that increases in M1 macrophages in the tumor microenvironment might inhibit MCF-7 cell growth." (PMID 32308723, 2020). "This indicated that LIPUS could reduce the metastasis of tumor by decreasing the expression levels of TNF-α and IL-6." (PMID 32936241, 2020). "In summary, our findings have revealed the link between IL-6/STAT3 pathway and CD73-adenosine axis, which might play an important role in tumor growth and chemoresistance in NPC." (PMID 32127934, 2020).
tumor (continued). "Furthermore, they modulate pro-tumorigenic inflammation through secretion of IL-1, IL-6, TNF-α, TGF-β, and CCL2, favoring tumor growth, angiogenesis, invasion and metastasis." (PMID 32499779, 2020). "Adipose tissue is highly metabolically active and secretes pro-inflammatory cytokines such as interleukin (IL)-6 and tumor necrosis factor (TNF)-alpha which may promote tumor initiation." (PMID 33327948, 2020). "CAFs—in EC—can trigger the expression of fibroblast activation protein (FAP) and, in turn, induces the secretion of IL-6 and CCL2 which are involved in creating an immune-suppressive tumor stroma, mainly characterized by M2 polarization of activated macrophages." (PMID 32751137, 2020). "Additionally, IL6/JAK/STAT3 signaling pathway has been proposed as one of the mechanisms that can affect tumor microenvironment and immune response to tumor cells." (PMID 33080912, 2020). "Like TNF-α, IL-6 facilitates tumor development by promoting the conversion of non-cancerous cells into cancer stem cells." (PMID 32283655, 2020). "Overall, physical activity resulted in a significant accumulation of tumor infiltrating immune cells, including natural killer cells, CD3+ T cells and dendritic cells, which appeared to be mediated, at least among natural killer cells, by IL-6 and epinephrine." (PMID 33597950, 2020). "Similar to CAF, TAM derived IL-6 amplifies undirected, that is, not tumor-targeted, inflammatory responses and promotes HCC via enhanced STAT3 signaling." (PMID 32899119, 2020). "Adipose tissue secretes leptin, VEGF, IL-1, IL-6, hepatocyte growth factor (HGF) and TNF-α that could induce tumor neoangiogenesis leading to the progression of solid tumors." (PMID 32977765, 2020). "Our canonical and functional pathway analyses of I-MDSCs showed that Wnt, IL-6, and MAPK signaling pathways are significantly upregulated in TT, compared with NT, suggesting a role of these pathways in tumor-infiltrating I-MDSCs within the CRC microenvironment." (PMID 31941522, 2020). "Indeed, CAF-secreted IGF-2 as well as IL-6 and IL-8 produced by CD-10+ GPR-77+ CAFs are promoting cancer stemness and tumor formation in lung cancer." (PMID 33553157, 2020). "In NPC, Zhang and co-workers demonstrated that interlukin 6/ signal transducer and activator of transcription 3 (IL6/Stat3) signaling may enhance the growth and tumorigenicity of EBV-positive tumor cells via the upregulation of the EBV LMP-1 viral protein." (PMID 32752071, 2020). "IL-6 acts as a key messenger between cancerous and non-cancerous cell populations at the tumour site." (PMID 33114676, 2020). "The significant positive correlation between IL-6 and GM-CSF with infiltration of CD33+S100a9+ cells indicates that these cytokines contribute to progression by modulating the immune composition of the tumour." (PMID 32747748, 2020). "When these spheroids were inoculated in immunodeficient mice the cocultured spheroids had faster tumor initiation and were less responsive to an IL-6 inhibitor than the homogenous spheroids which lacked monocytes." (PMID 33379189, 2020). "GALR2, a pro-survival G-protein coupled receptor promoted angiogenesis via p38-mediated phosphorylation/inactivation of TTP, resulting in increased VEGF and IL-6 levels both in vitro in SCCHN cancer cells and in vivo in murine tumor xenografts and chorioallantoic membrane models." (PMID 32545247, 2020). "This may come as a result of the tumor promoting activities of IL-17, which regulates the levels of VEGF-A and IL-6 promoting the proliferation of oral cancer cell." (PMID 35047982, 2020). "Besides IL‐6, other cytokine signaling components including IL‐8, TNF‐R, sIL‐2R, and M‐CSF have been shown to correlate with tumor grade and size in STS patients, and the serum levels of some of these proteins were associated with the prognosis." (PMID 33047515, 2020).